MANCR (mitotically associated long non coding RNA)
Synonyms: CR749391; LINC00704
Gene: Long non-coding RNA gene on chromosome 10 (4,579,241 to 4,678,216, reverse strand). Ensembl gene ENSG00000231298.
Diseases named in the same sentence as MANCR in open-access papers:
MANCR is named in the same sentence as 14 diseases in open-access papers, as found by Europe PMC text mining. Sharing a sentence is not in itself a finding about the gene and the disease. The quoted sentences say what the papers report.
breast carcinoma (7 papers, 2018 to 2022). "Previous studies demonstrated that MANCR was associated with the prognostic potential for breast cancer recurrence in a signature composed of 9 upregulated lncRNAs." (PMID 34418982, 2021). "MANCR (mitotically associated noncoding RNA) is upregulated in breast cancer, and downregulation of MANCR reduces TNBC cell proliferation." (PMID 34360879, 2021). "Upregulation of MANCR is significantly related to the poor prognosis of breast cancer via affecting the stability of the genome, leading to DNA damage and cell division defects." (PMID 35873456, 2022). "Previous studies have demonstrated that MANCR is highly expressed in gastric cancer and breast cancer and correlated with poor patient prognosis." (PMID 35873456, 2022).
gastric cancer (4 papers, 2021 to 2023). A primary or metastatic malignant neoplasm involving the stomach. "A study on gastric cancer demonstrated that high expression of MANCR predicted poor survival in patients." (PMID 34285140, 2021). "MANCR has been studied extensively in breast cancer, as well as in head and neck squamous cell carcinoma, thyroid cancer, prostate cancer, lung cancer, lymphoma, gastric cancer and ESCC." (PMID 38203269, 2023). "Moreover, upregulation of MANCR could predict poor prognosis in patients with gastric cancer." (PMID 33573176, 2021).
thyroid cancer (4 papers, 2018 to 2024). "Lu and colleagues revealed that higher MANCR (Mitotically associated long non coding RNA), also known as LINC00704, expression levels are associated with shorter overall survival time in thyroid cancer patients." (PMID 32760219, 2020). "To validate our analyses results, we chose an upregulated lncRNA LINC00704 which was also known as MANCR and investigated its function in thyroid cancer." (PMID 29923329, 2018).
prostate carcinoma (3 papers, 2021 to 2022). A carcinoma that arises from epithelial cells of the prostate gland. "Whereas, MANCR can also interact with protein to promote the migration and invasion of prostate cancer." (PMID 34285140, 2021). "The lncRNA MANCR has the same effect on prostate cancer, and JQ1 can downregulate MANCR to reduce cell migration and invasion." (PMID 34011395, 2021).
anaplastic thyroid cancer (1 paper, 2021). "Another study revealed that the predominant dysregulated pathways related to MANCR in regulating anaplastic thyroid cancer are relevant to mitosis and cell cycle." (PMID 34418982, 2021).
esophageal cancer (1 paper, 2025). A primary or metastatic malignant neoplasm involving the esophagus. "Conversely, downregulation of PDE4D expression was observed in esophageal cancer tissues, and it was found to bind with lncRNA MANCR promoting esophageal cancer cell proliferation and inhibiting cell apoptosis." (PMID 40129976, 2025).
mantle cell lymphoma (1 paper, 2022). Mantle cell lymphoma is a rare form of malignant non-Hodgkin lymphoma affecting B lymphocytes in the lymph nodes in a region called the ``mantle zone''. "Mechanistically, MANCR acts as a miRNA sponge to sequester miR-218, which targets RUNX2, in mantle cell lymphoma." (PMID 35893239, 2022).
cancer (6 papers, 2018 to 2023). A tumor composed of atypical neoplastic, often pleomorphic cells that invade other tissues. "To date, studies have illustrated that MANCR functions as an underlying biomarker in some cancers." (PMID 34418982, 2021). "In these settings, MANCR has been found to promote tumor growth, cancer cell proliferation, migration and invasion, leading to worse tumor characteristics and poor patient outcomes." (PMID 38203269, 2023). "We first used TCGA and the GTEx pan-cancer database to evaluate the expression level of MANCR in various cancer types." (PMID 35873456, 2022). "In this study, we identified differentially expressed MANCR from The Cancer Genome Atlas (TCGA) and Genotype-Tissue Expression (GTEx) databases across 24 cancer types and included 546 HNSCC patients." (PMID 35873456, 2022). "qRT-PCR indicated that MANCR was upregulated in different cancer cells, which indicated a good agreement with above bioinformatics analysis." (PMID 34418982, 2021). "LncRNA MANCR can lead to enhanced proliferative, invasive and migratory abilities of cancer cells while reducing cell apoptosis." (PMID 34418982, 2021). "The impact of MANCR on cancer cell biological behaviors was investigated via cell function experiments." (PMID 34418982, 2021). "The positive correlation between MANCR and immune infiltration cells may provide novel therapeutic targets and personalized immune-based cancer therapy for HNSCC." (PMID 35873456, 2022). "CCK-8 results suggested that downregulation of MANCR could significantly decrease the proliferative activity of cancer cells." (PMID 34418982, 2021). "Furthermore, in vitro experiments revealed that silencing MANCR inhibited cancer cell functions, blocked cell cycle progression while promoting cell apoptosis." (PMID 34418982, 2021). "Then, we examined the impact of MANCR on the functions of cancer cells." (PMID 34418982, 2021). "This study may promote further research examining MANCR as a target for cancer therapy purposes." (PMID 34418982, 2021). "Our study supports the suggestion that MANCR is upregulated in EAC patients, which is compatible with the findings in other cancer types." (PMID 38203269, 2023). "Therefore, it was revealed that MANCR could stimulate cancer cell invasion and migration." (PMID 34418982, 2021). "Differences in MANCR expression have not been extensively studied in cancer as regards their role in tumor staging and tumor characteristics." (PMID 38203269, 2023). "MANCR may also serve as a pivotal target for the bromodomain and extra-terminal (BET) protein BRD4, exerting a crucial influence on cellular migration and the invasive properties of cancer." (PMID 38203269, 2023).
tumor (6 papers, 2018 to 2023). "Therefore, comprehensive studies on the association of tumor-infiltrating immune cells, immunomodulators, and MANCR in HNSCC are needed." (PMID 35873456, 2022). "Here, by data mining analysis from TCGA and the GTEx database, the upregulation of MANCR was observed in 17 types of tumor tissues compared with adjacent normal tissues, including HNSCC." (PMID 35873456, 2022). "In hepatocellular carcinoma, MANCR could promote the tumor cell proliferation process by regulating miR-122a." (PMID 35873456, 2022). "The dysregulated expression levels of MANCR were reported in thyroid carcinoma, gastric carcinoma, and esophagus cancer, thus enhancing tumor malignant development." (PMID 35873456, 2022). "These indicated that MANCR expression was remarkably related to tumor size and metastasis." (PMID 34418982, 2021). "In summary, in order to translate our results into clinical practice, we have shown that MALAT1, MANCR and miR-101 hold promise as potential prognostic indicators for EAC patients, depicting worse survival and worse tumor staging when dysregulated." (PMID 38203269, 2023). "Combined with the patient’s clinical information, MANCR expression displayed remarkable differences in T stage, N stage, and different clinical stages of LUAD and showed an upward trend as tumor stage increases." (PMID 34418982, 2021). "Assessment of MANCR expression in relation to grade and size of the tumor did not produce a statistically significant result (p = 0.07 and p = 0.21, respectively)." (PMID 38203269, 2023).
MANCR also shares sentences with these, for which no sentence is quoted: esophageal adenocarcinoma (1 paper); head and neck squamous cell carcinoma (1); hepatocellular carcinoma (1); lung adenocarcinoma (1); lung carcinoma (1).